USP22 (ubiquitin specific peptidase 22)
Diseases named in the same sentence as USP22 in open-access papers (continued):
Sharing a sentence is not in itself a finding about the gene and the disease.
gastric cancer (continued). "To select appropriate cell lines for exploring the function of USP22 in gastric cancer, we measured endogenous mRNA levels in various gastric cancer cell lines." (PMID 32063746, 2020). "To further validate the overexpression of USP22 in gastric cancer, we collected the mRNA expression data from the TCGA database." (PMID 32063746, 2020). "To further explore the role of USP22 in gastric cancer, we examined cell apoptosis and cell cycle progression in USP22-overexpressing or -silenced gastric cancer cells." (PMID 32063746, 2020). "In this study, we demonstrate that USP22 is highly expressed in gastric cancer tissue, compared with adjacent normal tissue." (PMID 32063746, 2020). "In this study, we measured the protein expression of USP22 in gastric cancer tissue in patients with primary gastric cancer and evaluated the correlation between USP22 expression and clinicopathologic characteristics." (PMID 32063746, 2020). "USP22 protein expression was significantly increased in human gastric cancer tissues, compared with adjacent normal tissues, and was positively correlated with local tumor stage." (PMID 32063746, 2020). "To explore the involvement of USP22 in gastric cancer, we examined the protein expression of USP22 in 88 samples of gastric cancer tissue and paired adjacent normal tissue from patients with primary gastric cancer." (PMID 32063746, 2020). "Knockdown of RAS activator son of sevenless 1 (SOS1) was performed to investigate the role of SOS1 in USP22-regulated gastric cancer cell behavior and RAS signaling both in vitro and in vivo." (PMID 32063746, 2020). "Gene sequencing data have revealed that USP22 mRNA expression is frequently reduced in some cancers, including ovarian, esophageal, and stomach cancers." (PMID 32063746, 2020). "USP22 overexpression in gastric cancer cells induces the upregulation of SOS1 and activation of the RAS/ERK and PI3K/AKT pathways." (PMID 32063746, 2020). "We also evaluated the effects of USP22 overexpression and knockdown on the malignant behaviors of gastric cancer cells both in vitro and in vivo." (PMID 32063746, 2020). "USP22 overexpression occurs in many cancer types, including gastric cancer, playing oncogenic roles via multiple mechanisms, such as the activation of transcription factors, the attenuation of cancer cell apoptosis, and promotion of the cell cycle transition." (PMID 32063746, 2020). "Taken together, our study demonstrates that USP22 is indispensable for gastric cancer stem cell self-renewal through stabilization of BMI1." (PMID 28415621, 2017). "Immunofluorescence staining of gastric cancer tissues also showed strong nuclear co-localization of USP22 and BMI1." (PMID 28415621, 2017). "Further, RNA-sequencing data also show that USP22 mRNA expression is more frequently reduced in ovarian, esophagus, breast, colorectal, pancreatic and stomach cancers." (PMID 29210986, 2017). "In this study, we found that silencing of USP22 inhibited proliferation of gastric cancer cells and suppressed the cancer stem cell spheroid formation in serum-free culture." (PMID 28415621, 2017). "In gastric cancer, USP22 maintains CSC stemness by stabilizing BMI1 protein." (PMID 35935969, 2022). "The expression pattern of USP22 in human gastric cancer was detected in a tissue microarray containing 88 pairs of gastric cancer tissue and adjacent normal tissue samples from patients with primary gastric cancer using immunohistochemical staining." (PMID 32063746, 2020). "Targeting the USP22/SOS1/RAS axis represents a promising strategy in gastric cancer therapy." (PMID 32063746, 2020). "To investigate whether SOS1 plays an essential role in mediating the tumorigenic roles of USP22 in gastric cancer, we silenced its expression in USP22-overexpressing SGC7901 cells." (PMID 32063746, 2020).
gastric cancer (continued). "Furthermore, SOS1 upregulation in USP22-overexrpessing gastric cancer cells and xenograft tumor tissue is accompanied by activation of the RAS/ERK and RAS/PI3K/AKT pathways, which is attenuated by SOS1 silencing." (PMID 32063746, 2020). "Clarifying the expression and activity of USP22 in gastric cancer is critical to determine whether targeting USP22 will be beneficial for patients." (PMID 32063746, 2020). "Our findings identify the USP22/SOS1/RAS axis as a promising therapeutic target in gastric cancer." (PMID 32063746, 2020). "The oncogenic role of USP22 in gastric cancer relies on SOS1 expression." (PMID 32063746, 2020). "Furthermore, the results of flow cytometry showed that USP22 overexpression increases the proportion of gastric cancer cells in the G2/M phase, whereas USP22 silencing reduces this proportion." (PMID 32063746, 2020). "Next, we performed a loss-of-function assay to investigate whether SOS1 plays an essential role in the oncogenic effects of USP22 on gastric cancer cells." (PMID 32063746, 2020). "In this study, the results of a ChIP assay allowed us to demonstrate for the first time that USP22 may interact with RAS activator SOS1 in gastric cancer." (PMID 32063746, 2020). "The correlation of USP22 expression with clinicopathological features of gastric cancer." (PMID 31689236, 2019). "Furthermore, we found that overexpression of USP22 stabilized the BMI1 protein in gastric cancer cells." (PMID 28415621, 2017). "Additionally, overexpression of miR-200b-5p, a regulator of USP22, suppresses gastric cancer cell proliferation and migration by targeting the NF−κB pathway, highlighting its potential as a new therapeutic target in gastric cancer." (PMID 40370434, 2025). "In addition, the USP22/SOS1/RAS axis is also a cancer-promoting pathway in gastric cancer." (PMID 35935969, 2022). "Furthermore, our study indicated that SOS1 was upregulated in USP22-overexpressing gastric cancer cells and xenograft tumor tissue, accompanied by activation of the RAS/ERK and PI3K/AKT pathways, suggesting that SOS1/RAS signaling mediates the oncogenic role of USP22 in gastric cancer." (PMID 32063746, 2020). "Furthermore, SOS1 silencing could reverse the effects of USP22 on gastric cancer cell behavior and RAS signaling both in vitro and in vivo." (PMID 32063746, 2020). "Additionally, knockdown of USP22 inhibited gastric cancer xenografts growth." (PMID 28415621, 2017). "In GC, co-expression of USP22 and BMI1 was prognostic for gastric cancer progression and treatment failure." (PMID 28415621, 2017). "In stomach cancer, USP22 abundance increased from normal tissue to primary carcinoma to lymph node metastasis and was also associated with shorter patient survival (26 vs. 59 months disease-specific survival for USP22-positive vs. -negative primary carcinoma)." (PMID 29210986, 2017). "It has been reported that there is a correlation between the level of ubiquitin-specific protease 22 (USP22) and the clinicopathological parameters and prognosis of gastric cancer (GC) patients, but the conclusions are inconsistent." (PMID 35784926, 2022). "USP22 maintains stemness of CSC and promotes gastric cancer development through stabilizing the BMI1 protein." (PMID 34753387, 2021). "Our results suggest that USP22 acts as an oncogene in gastric cancer in a SOS1-dependent manner, identifying the USP22/SOS1/RAS axis as a potential therapeutic target in gastric cancer." (PMID 32063746, 2020). "Our findings identify the USP22/SOS1/RAS axis as a novel and promising therapeutic target in gastric cancer." (PMID 32063746, 2020). "In this study, we investigated the role of ubiquitin-specific protease 22 (USP22) in the growth and progression of gastric cancer (GC)." (PMID 31689236, 2019).
gastric cancer (continued). "It has been reported that both USP7 and USP22 protect PD-L1 from ubiquitination-mediated degradation in cancers including gastric cancer, lung adenocarcinoma, and liver cancer, neither of which was enriched in our screening." (PMID 38038129, 2023). "Co-expression of USP22 and BMI1 could accelerate tumor development, stemness and predict therapy failure in gastric carcinoma." (PMID 34753387, 2021). "Our analysis of TCGA database indicated that BMI1 overexpression may predict gastric cancer patient survival, and TAT-BMI1 proteins reversed the USP22 knockdown-mediated decreased in cancer stem cell properties, and elevated the expression of stemness-associated genes." (PMID 28415621, 2017).
lung adenocarcinoma (17 papers, 2017 to 2025). A carcinoma that arises from the lung and is characterized by the presence of malignant glandular epithelial cells. "NF-YA is also found to be involved in USP22 expression in lung cancer, while global overexpression of NF-YA is documented in lung adenocarcinoma and is associated with aggressive cancer behavior." (PMID 36123698, 2022). "Cisplatin-resistant lung adenocarcinoma cells were shown to be associated with upregulation of USP22." (PMID 34660907, 2020). "Ubiquitin-specific protease 22 (USP22) expresses highly in lung adenocarcinoma (LUAD), which are associated with poor overall survival (OS)." (PMID 32294625, 2020). "Overexpression of USP22 protein has been reported in numerous cancers including lung adenocarcinoma, and is associated with poor prognosis of cancer patients." (PMID 31842906, 2019). "We recently showed that frequent loss of H2Bub1 is significantly associated with aggressive tumor biology in lung adenocarcinoma, and USP22 protein is enriched and plays critical role in cancer stem cells isolated from primary lung adenocarcinoma." (PMID 31842906, 2019). "In addition, we recently found that expression of USP22 is associated with cisplatin resistance in cancer-initiating cells (CIC) from primary lung adenocarcinoma." (PMID 31842906, 2019). "The previous study confirms that ubiquitin‐specific protease 22 (USP22) promotes lung adenocarcinoma (LUAD) metastasis in vivo and in vitro." (PMID 39101247, 2024). "In lung adenocarcinoma, USP22 inhibition decreases ALDH1A3 expression, heightens the sensitivity of tumor cells to cisplatin, particularly CD133+ cancer-initiating cells, and attenuates their stem cell-like properties." (PMID 38702734, 2024). "In lung adenocarcinoma, USP22, adeubiquitinase highly overexpressed in multiple cancer types, has been shown tomodulate PALB2 levels through its C-terminal WD40 domain to promotechemoresistance." (PMID 35293552, 2022). "In the study of the correlation between USP22 and acquired cisplatin resistance in lung adenocarcinoma, the expression of USP22 was found to be upregulated in cisplatin-resistant lung adenocarcinoma cells." (PMID 35935969, 2022). "Using HR and NHEJ reporter system, we herein found that USP22 knockout significantly impaired NHEJ repair potential in lung adenocarcinoma cells." (PMID 31842906, 2019). "In this study, we also found that USP22 is upregulated in lung adenocarcinoma; and upregulation of USP22 protein was more frequently found in advanced stage and was associated with the recurrence of NSCLC, indicating USP22 plays oncogenic roles in NSCLC." (PMID 31842906, 2019). "And compared with the parent cells, USP22 knockout induced cell-cycle arrest and significantly suppressed both in vitro and in vivo of lung adenocarcinoma growth." (PMID 31842906, 2019). "USP22 is a potential target in cisplatin-resistant lung adenocarcinoma and should be considered in future therapeutic practice." (PMID 28567015, 2017). "Our study confirmed that the overexpression of USP22 was correlated with acquired resistance to cisplatin in lung adenocarcinoma." (PMID 28567015, 2017). "This study focused on the relationship between USP22 and cisplatin resistance in lung adenocarcinoma and explored the potential mechanisms to provide a new therapeutic target for reversing cisplatin resistance." (PMID 28567015, 2017). "The present study aimed to investigate the correlation of ubiquitin-specific peptidase 22 (USP22) with acquired resistance to cisplatin in lung adenocarcinoma." (PMID 28567015, 2017). "In conclusion, USP22 is a potential target in cisplatin-resistant lung adenocarcinoma and should be considered in future therapeutic practice." (PMID 28567015, 2017). "Additionally, studies indicate that miR-30b-5p targets USP22 to inhibit hypoxia-induced PD-L1 expression in lung adenocarcinoma cells." (PMID 40018039, 2025).
lung adenocarcinoma (continued). "In lung adenocarcinoma cells, the deubiquitinase USP22 stabilizes COL17A1 protein by enhancing COL17A1 deubiquitination to upregulate COL17A1 and thus promotes cell growth, invasion, and migration and suppresses cell apoptosis and ferroptosis, leading to this disease progression." (PMID 39143031, 2024). "However, upregulation of USP22 in lung adenocarcinoma inhibits Bax-mediated apoptosis in cisplatin-resistant cells." (PMID 34660907, 2020). "Interestingly, it was described that USP22 knockdown sensitized lung adenocarcinoma tumor spheres towards cisplatin treatment." (PMID 31801945, 2019). "The precise mechanisms through which USP22 affects cancer progression are largely unknown in lung adenocarcinoma." (PMID 31842906, 2019). "Additionally, H2A deubiquitinase USP22 was reported to promote tumor progression and induces epithelial-mesenchymal transition in lung adenocarcinoma." (PMID 28498834, 2017). "In this study, we for the first time showed that AP2 is an important transcription factor driving USP22 gene expression; and revealed an association of AP2 with USP22 in lung cancer tissues, suggesting AP2 may promotes the progression of lung adenocarcinoma partially via enhancing USP22 expression." (PMID 36123698, 2022). "Our findings in lung adenocarcinoma cell line and xenografts support that USP22 could promote the phosphorylation of histone H2AX via deubiquitinating histone H2A, thus contributing to the DNA damage repair induced by cisplatin and leading to cisplatin resistance." (PMID 28567015, 2017). "However, is USP22 also involved in the process of cisplatin resistance in lung adenocarcinoma?" (PMID 28567015, 2017). "Ubiquitin-specific peptidase 22 (USP22) deubiquitinates and phosphorylates H2AX to enhance DNA damage repair and induce cisplatin resistance in lung adenocarcinoma." (PMID 36694209, 2023). "USP22, a crucial regulator that enhances H2AX phosphorylation through its deubiquitinating activity, has been shown to contribute to robust DDR mechanisms in lung adenocarcinoma." (PMID 38702734, 2024). "Ubiquitin-specific protease 22 (USP22) has been shown to prevent ubiquitination-mediated EGFR degradation and activate multiple EGFR downstream signaling pathways, thus conferring resistance to EGFR-TKIs in mutant lung adenocarcinoma cells." (PMID 36694209, 2023). "USP22 is highly expressed in lung adenocarcinomas compared to normal mucosa." (PMID 35935969, 2022).
non-small cell lung carcinoma (14 papers, 2015 to 2025). A group of at least three distinct histological types of lung cancer, including non-small cell squamous cell carcinoma, adenocarcinoma, and large cell carcinoma. "Alike, it was revealed that miR-30e-5p depletes the occurrence of non-small cell lung cancer by downregulating ubiquitin-specific peptidase 22 and affecting the sirtuin 1/Janus kinase/signal transducer and activator of transcription 3 signaling pathway." (PMID 35300562, 2022). "In non-small cell lung cancer, USP22 can directly deubiquitinate PD-L1 and regulate the level of PD-L1 through the USP22-CSN5-PD-L1 axis, resulting in decreased T-cell proliferation and activation." (PMID 34179009, 2021). "Human non-small cell lung cancer cells and 293FT cells were used to investigate the function of USP22 upon PD-L1 and CSN5 by WB, Immunoprecipitation, Immunofluorescence and Flow cytometry analysis." (PMID 32665011, 2020). "In non-small cell lung cancer (NSCLC), the upregulation of USP22 was reported to be associated with advanced stage or recurrent NSCLC and considered as a poor prognostic marker for overall survival." (PMID 34660907, 2020). "The relationship between USP22 and PD-L1 expression was investigated by Immunohistochemistry analysis in human non-small cell lung cancer samples." (PMID 32665011, 2020). "To further validate the pathologic relevance of USP22 and PD-L1, we studied the expression of USP22 and PD-L1 in 241 human non-small cell lung cancer samples using immunohistochemical staining." (PMID 32665011, 2020). "USP22 overexpression is detected in many human tumors, including non-small cell lung cancer, salivary duct carcinoma, bladder cancer, colorectal cancer, oral squamous cell carcinoma, and esophageal squamous cell carcinoma." (PMID 27145278, 2016). "Similarly, in non-small cell lung cancer, USP22 inhibition improves gefitinib sensitivity and induces ferroptosis, offering a novel strategy to overcome chemoresistance." (PMID 40370434, 2025). "Besides, USP22 expression positively correlated with PD-L1 expression in human non-small cell lung cancer samples." (PMID 32665011, 2020). "USP22 has been shown to promote the proliferation of human non-small cell lung cancer cell H1129 and human bladder cancer cell EJ by facilitating cell cycle progression, which was supported by the observed G1 phase arrest and concomitant reduction in the S and G2/M phase when USP22 was depleted." (PMID 27145278, 2016). "Notably, other USP family members—including USP22, USP10, and USP32—have been associated with adverse prognosis in various malignancies, including pancreatic ductal adenocarcinoma, non-small cell lung cancer." (PMID 40926837, 2025).